GRIN2B (glutamate ionotropic receptor NMDA type subunit 2B)
Diseases named in the same sentence as GRIN2B in open-access papers (continued):
Sharing a sentence is not in itself a finding about the gene and the disease.
epilepsy (continued). "Our data show that the new rat Grin2b haploinsufficiency model exhibits clinically relevant phenotypes and highlights two potential therapeutic options for GRIN2B‐related epilepsy." (PMID 40827489, 2025). "Overexpression of GRIN2B results in NMDA receptor hyperactivation and serves as a risk factor for epilepsy." (PMID 39684851, 2024). "Mutations in GRIN1 (encodes the GluN1 subunit), GRIN2B (encodes the GluN2B), and GRIN2D (Glu N2D) present with severe clinical phenotypes, including severe epilepsy with mental retardation and developmental delay." (PMID 36979762, 2023). "Genes most commonly impacted by pdSNV included GRIN2B (n = 6), which is reported in individuals with ID, epilepsy, and ASD." (PMID 34615535, 2021). "Looking into the DEG subnetwork, we found that some well-known ASD candidate genes, such as Kcnma1, Shank2, Cacna1a and Cacna1b, and epilepsy candidate genes, such as Scn3a, Grin2a, Gabrg2, and Grin2b, are hub genes in this subnetwork." (PMID 32033586, 2020). "Genetic variants in the GluN2B gene, GRIN2B, have been implicated in sporadic ASD, while mutations of GRIN2B and GRIN2A (the GluN2A gene) have been associated with epilepsy and intellectual disability." (PMID 27134685, 2016). "The effectiveness of memantine on drug‐resistant early‐onset epilepsy in individuals with gain‐of‐function GRIN2 variants (GRIN2A, GRIN2B and GRIN2D) is mixed, and previously, memantine treatment did not improve seizure frequency in four patients with GRIN2B gain‐of‐function mutations." (PMID 40827489, 2025). "By incorporating all cases from our center and those reported in the literature, we conclude that the phenotypic spectrum of GRIN2B is broad, which is characterized by DD/ID, epilepsy, hypotonia, language impairment, movement disorders, and behavioral disturbances." (PMID 41146259, 2025). "Overall, our results highlight the benefits of memantine in treating GRIN2B-related epilepsy." (PMID 41146259, 2025). "Genes encoding NMDAR subunits (such as GRIN1, GRIN2A, and GRIN2B) have been identified to be associated with broad-spectrum phenotypes, including epilepsies, epilepsies with NDD, and NDD without seizures." (PMID 38249294, 2023). "Indeed, we report for the first time post-operative seizure outcomes for six genetic causes of epilepsy: COL4A1, GRIN2B, NEXMIF, NSD1, SCN2A and SLC9A6." (PMID 37264783, 2023). "After searching in DrugBank, we retrieved a total of 47 anti-epileptic drugs and 151 targets, of which identified 17 target genes (CACNA1A, CHRNA4,CHRNA7,GABRA1,GABRA2,GABRB2,GABRG2,GRIK1,GRIN1,GRIN2B,KCNQ2,KCNQ3,SCN1A,SCN2A, SCN3A,SCN8A and SCN9A) were overlapped with risk genes of epilepsy." (PMID 36006933, 2022). "Aetiological overlap between ID and epilepsy is well known and could potential explain the phenotypic differences across patients, as evidenced by dominant pathogenic variants in HECW2 and GRIN2B." (PMID 33603162, 2021). "Consistent with the converged network module of the PPI subnetworks for autism, epilepsy, and learning/memory, the shared module of these three gene-pathway bipartite subnetworks also involve NMDARs (Grin1, Grin2a, and Grin2b) as hubs connecting to 16 pathways." (PMID 32033586, 2020). "In addition to DD/ID and epilepsy, ASD was the most commonly observed phenotype, which may be due to structural abnormalities in neuronal synapses caused by GRIN2B variants." (PMID 41146259, 2025). "However, different from those in epilepsy, GRIN2B but not GRIN2A variants are mostly associated with ID." (PMID 35680847, 2022). "A related study demonstrated that GRIN2B, BDNF, and IL-1β gene significantly were upregulated and GRIN2B was positively correlated with the expressions of BDNF and IL-1β gene in people with epilepsy." (PMID 35069111, 2021).
epilepsy (continued). "Lethal status epilepticus was reported in juvenile mice lacking GluN2B specifically in inhibitory neurons, and although significant, this observation does not effectively translate to the pan neuronal impact of GRIN2B mutations in patients with epilepsy." (PMID 40827489, 2025). "An effective treatment option for GRIN2B-related epilepsy is still lacking." (PMID 41146259, 2025).
depression (78 papers, 2009 to 2025). "Another study suggests the increased synthesis of synaptic proteins and relief in behavioral symptoms of depression upon knock out of the GRIN2B gene (located on 12p13.1), which encodes the GluN2B subunit." (PMID 35456452, 2022). "A GWAS study has suggested that GRIN2B (based on SNP rs220549) is a potential candidate gene that is linked with the onset of depression in MDD patients." (PMID 35456452, 2022). "For this reason, GRIN2B mRNA level is rather considered as biomarker of suicide and, in fact, polymorphisms of GRIN2B have been postulated to predict treatment-resistant depression." (PMID 32585886, 2020). "In pharmacological interventions, the same variant of NMDAR (GRIN2B) has been proposed to act as a genetic predictor of treatment-resistant depression (TRD) in patients with major depressive disorder (MDD)." (PMID 26819771, 2016). "Other variants of the GRIN2B gene have been associated with treatment resistant depression." (PMID 39297975, 2025). "GRIN2B variants have been associated with treatment-resistant depression." (PMID 41465140, 2025). "A genome-wide association study in European samples has demonstrated that rs220549 in GRIN2B is associated with depression, suggesting GRIN2B may be a promising candidate gene for MDD." (PMID 36142247, 2022). "We conducted PheWAS cross-phenotype searches for the five drug target genes in a hypothesis-free manner and found association between GRIN2B and multiple depression-related phenotypes." (PMID 34301328, 2021). "Therefore, it is conceivable that the association between GRIN2B and depression related phenotypes were obtained because the web survey contained multiple questions relating to depression-related mental states." (PMID 34301328, 2021). "Association was found between GRIN2B and multiple phenotypes related to depression, which is considered reliable based on previous reports on the biological function of GRIN2B protein and its relationship with depression." (PMID 34301328, 2021). "Additionally, polymorphisms of the GluN2B gene (GRIN2B) have been considered to be prediction factors of antidepressant-resistant depression." (PMID 33114753, 2020). "After the multiple comparison correction by 1,000 permutation tests, GRIN1 (rs4880213) was significantly associated with depression (P = 0.04) and disruptive behavior (P = 0.04), and GRIN2B (rs7301328) was significantly associated with disruptive behavior (P = 0.05)." (PMID 26819771, 2016). "Furthermore, associations between GRIN2B and multiple phenotypes related to depression were found." (PMID 34301328, 2021). "Moreover, compared with non-suicidal patients with MDD, the expression of the human gene GRIN2B, encoding the NMDAR GluN2B subunit in the brain of suicidal depression patients, is increased—suggesting that GRIN2B could be a candidate gene for susceptibility to MDD." (PMID 36291261, 2022). "Five important depression targets identified using the network map (GRIN2B, GRIN2A, DRD2, SLC6A4, and MAOA) and twenty-one related active compounds were selected for molecular docking." (PMID 33746756, 2021). "On the other hand, in the frontal cortex, BDNF deficiency, which occurs under chronic stress and is one of the leading causes of depression, also increased the density of GRIN1, GRIN2A and GRIN2B genes in the early stages of development." (PMID 32585886, 2020). "Particularly, genetic studies suggested the involvement of GRIN2B, which encodes the critical structural and functional NR2B subunit of NMDA receptors, in bipolar disorder and as a genetic predictor for treatment-resistant depression in major depressive disorder." (PMID 32504122, 2020). "Since Grin2b is involved in long-term potentiation and there is an association between Grin2b single nucleotide polymorphisms (SNPs) and MDD, it may provide evidences for the role of this gene in memory loss of patients with depression." (PMID 25423262, 2014).
depression (continued). "Also, NMDA (N-methyl-D-Aspartate) receptors Grin2a (Glutamate receptor ionotropic, NMDA 2A) and Grin2b (Glutamate receptor ionotropic, NMDA 2B) play key role in the pathology of mood disorders and their polymorphisms could be associated with depression." (PMID 25423262, 2014). "However, dysregulation of SETDB1 activity and its downstream pathway (for example, the repression of Grin2b that encodes NMDA receptor NR2B) might be involved in the progression of neuropathology of symptoms of depression under negative environmental impacts." (PMID 32321908, 2020). "Comparison of suicides with major depressive disorder to non-suicide patients again showed that the expression of glutamate receptors (GRIN2B, GRIK3 and GRM2) was higher in suicides." (PMID 39297975, 2025). "Nevertheless, when male and female patients were grouped, the expression of GRIN2B mRNA was higher in those who committed suicide, in comparison with those that suffered depression but did not die by suicide." (PMID 32585886, 2020). "Additional examples include schizophrenia for RELN, GluR6, GRIN2A, GRIN2B, and CNTNAP2, childhood absence epilepsy for GABRB3, ADHD and depression for 5-HTT, and major depression for TPH2." (PMID 23935565, 2013).
Alzheimer disease (48 papers, 2009 to 2025). A progressive, neurodegenerative disease characterized by loss of function and death of nerve cells in several areas of the brain leading to loss of cognitive function such as memory and language. "GRIN2B, which encodes a N-methyl D-aspartate (NMDA) receptor GluN2B subunit, is a target of memantine, used to treat moderate to severe dementia in patients with Alzheimer’s disease." (PMID 38028628, 2023). "The mRNA levels of Grin2b, however, increased in response to PL, which contradicts results from aged mice and a mouse model of Alzheimer’s disease." (PMID 35216124, 2022). "Previous studies have shown that GRIN2B, a target gene of nuclear respiratory factor 1, plays a role in Alzheimer’s disease." (PMID 31611906, 2019). "Hypermethylation in the promoters of MME and GRIN2B were previously reported to contribute to Alzheimer’s disease and seizures, respectively." (PMID 25997610, 2015). "We identified several proteins involved in the Alzheimer's disease pathway, including NMDA receptor (NMDARs) subunits (GRIN1, GRIN2B, and GRIN2D)." (PMID 40047119, 2025). "ADAM17, BACE1, CAPN1, CDK5, EIF2AK3, GRIN2B, and GSK3B were enriched in the Alzheimer disease pathway (hsa05010)." (PMID 33807157, 2021). "In addition, decreased levels of GluN2B protein are correlated with advanced age in the hippocampus of aging mice and decreased levels of GRIN2B mRNA during Alzheimer's disease progression." (PMID 28439047, 2017).
Anxiety (48 papers, 2010 to 2026). Intense feelings of nervousness, tension, or panic often arise in response to interpersonal stresses. "Moreover, glutamate ionotropic receptor NMDA type subunit 2b (GRIN2B) is associated with anxiety-like behaviour in mice when juvenile mice were fed a methyl-donor-deficient diet." (PMID 35144563, 2022). "In line with this idea, Grin2b is widely expressed in the brain, and anxiety-like behavior has been associated with various brain regions, including the hippocampus, anterior cingulate cortex, lateral septum, bed nuclei of the stria terminalis, paraventricular nucleus, and basolateral amygdala." (PMID 32353004, 2020). "Behaviorally, Grin2b+/Δ mice exhibited hypoactivity, increased anxiety in males, and impaired sensorimotor gating in both sexes, while learning, memory, and social behaviors remained largely intact." (PMID 41615455, 2026). "Examining the mRNA SLC1A2, SLC1A3, GRM5, GRIN2B, GRIN2C, GRIA1, CHRNA7, 5-HT2A, and 5-HT3A offers insight into the neurotransmission systems implicated in NP-related anxiety." (PMID 41515464, 2026). "Especially in dominant female mice compared to their submissive counterparts, genes involved in modulating fear response and anxiety (e.g., Cacna1e, Nlg2, Tnr, Grin2a, and Grin2b) were up-regulated." (PMID 34490254, 2021). "Similar behaviors include hypoactivity in the open-field test and normal anxiety-like behavior in open-field and light-dark tests, but anxiolytic-like behavior of Grin2b+/–mice in the elevated plus-maze was much weaker than that in Grin2b+/C456Y mice." (PMID 32353004, 2020). "Adult Grin2b+/C456Y mice show anxiolytic-like behavior in the elevated plus-maze test but normal anxiety-like behaviors in open-field and light-dark tests." (PMID 32353004, 2020). "This suggests that Grin2b+/C456Y pups display anxiety-like behaviors, similar to the anxiety symptoms comorbid with human ASD." (PMID 32353004, 2020). "After being fed a diet supplemented with methyl donors ad libitum, adult mice reversed the alteration of gene expression of Dnmt3a, Dnmt3b, Grin2b and Gabar2, but anxiety-like behavior became elevated." (PMID 25144567, 2014). "Likewise, the neurotrophic factor Bdnf has long been associated with synaptic plasticity and cognitive function, and has also been shown to play a role in anxiety-related behaviors alongside Grin2b." (PMID 38357099, 2024). "In addition to cognitive processes such as attention, learning and memory, Grin2b and its product have also been shown to affect emotionality/anxiety." (PMID 36056863, 2023). "Future experiments evaluating the sensitivity to compounds acting on the NMDA receptor may also help to determine the function of Grin2b on the emotionality/anxiety and hyperactivity differences among LEW, SHR, and SLA16 rats." (PMID 36056863, 2023). "However, upon mother separation and reunification in a mother-homing test, Grin2b+/C456Y juveniles spent normal amounts of time with the reunited mothers, suggestive of normal anxiety-like behaviors." (PMID 32353004, 2020). "How the early anxiety-like behavior in Grin2b+/C456Y pups is weakened or reversed as the pups grow into juveniles and adults remain unclear." (PMID 32353004, 2020). "Therefore, anxiety-like behavior in Grin2b+/C456Y pups seems to be strongly weakened or changed into anxiolytic-like behavior at juvenile stages, similar to the anxiolytic-like behaviors in adults." (PMID 32353004, 2020). "Consistent with this, GEG also attenuated expression of excitotoxic N-methyl-D-aspartate (NMDA) receptor subunits GRIN2B and GRIN2C in the frontal cortex and hypothalamus, thereby reflecting impaired neuroplasticity and neurotoxicity that have been implicated in pain hypersensitivity and anxiety." (PMID 41515464, 2026).
Anxiety (continued). "Therefore, the anxiety-like behavior of Grin2b+/C456Y pups seems to be rapidly weakened as these mice grow up, whereas self-grooming slowly develops at an adult stage, pointing to the contrasting trajectories of two important ASD-related phenotypes (anxiety-like behavior and self-grooming)." (PMID 32353004, 2020). "In contrast, Grin2b+/C456Y pups display strongly increased USV calls upon mother separation, suggestive of anxiety-like behavior." (PMID 32353004, 2020). "Grin2b+/C456Y mice display decreased GluN2B levels at an adult stage (P56), suggesting that the continuing decrease in GluN2B levels in adult mutant mice, in addition to the reduced LFS-LTD in young mutant mice, might be associated with anxiety-like behavior or hypoactivity." (PMID 32353004, 2020). "The effect of late chronic D-cycloserine treatment in adult Grin2b+/C456Y mice could not be tested because the chronic treatment procedure seemed to increase anxiety levels in these mice, blunting the baseline difference between WT and mutant mice." (PMID 32353004, 2020).
Intellectual disability (41 papers, 2012 to 2026). "In humans, variants in the GRIN2B gene have been associated with impaired cognitive phenotypes such as intellectual disability, and developmental delay." (PMID 30475886, 2018). "Additionally, research using mouse models of neurodevelopmental disorders has shown that GRIN2B mutations can manifest in autism spectrum disorders and intellectual disabilities and are often accompanied by abnormal sleep behaviors, including SB." (PMID 39684851, 2024). "Notably, individuals with missense mutations in GRIN2B develop rare autosomal dominant forms of encephalopathy characterize by intellectual disability, impaired learning, and behavior phenotypes." (PMID 38028628, 2023). "GRIN2B mutations have been found in patients with autism, cerebral visual impairment, West syndrome and intellectual disability." (PMID 29365063, 2018). "Mutations in GRIN2B cause intellectual disability and language impairments." (PMID 29937144, 2018). "The NMDA subunit NR2B, encoded by GRIN2B, has been implicated in cases of mental retardation." (PMID 26020650, 2015). "Pathogenic variants in GRIN2B, encoding the NMDA receptor (NMDAR) GluN2B subunit, are linked to intellectual disability (ID) and related neurodevelopmental disorders." (PMID 41615455, 2026). "Specifically, genetic defects in GRIN2B are primarily correlated with neurodevelopmental disorders, including developmental delay (DD), intellectual disability (ID), and autism spectrum disorder (ASD), as well as schizophrenia-like phenotypes." (PMID 41146259, 2025). "Most individuals with GRIN2B-related neurodevelopmental disorder present with intellectual disability and developmental delay." (PMID 36704660, 2022). "Further clinical exome sequencing identified a de novo pathogenic variant in GRIN2B (MIM *138252) in the proband, which completely explained the phenotype, i.e. intellectual disability with a psychiatric disorder (MIM #613970)." (PMID 33767182, 2021). "In the present study, we generated and characterized a knock-in mouse line carrying an ASD-risk mutation (GluN2B-C456Y) in the Grin2b gene, a de novo mutation identified in a male individual with ASD and intellectual disability." (PMID 32353004, 2020). "Heterozygous loss-of-function mutations in GRIN2B, a subunit of the NMDA receptor, cause intellectual disability and language impairment." (PMID 29937144, 2018). "Genetic and bioinformatic analyses have identified missense mutations in GRIN2B encoding the NMDA receptor GluN2B subunit in autism, intellectual disability, Lennox Gastaut and West Syndromes." (PMID 29511171, 2018). "For example, GRIN1 and GRIN2B patients can present with mild or severe intellectual disabilities." (PMID 39535073, 2025). "Mutations in GRIN1 (which encodes the GluN1 subunit), GRIN2B (GluN2B), and GRIN2D (GluN2D), expressed during embryonic development, display more severe clinical phenotypes, including severe intellectual disability and developmental delay, than GRIN2A (GluN2A) mutations." (PMID 32197322, 2020). "Defects in the GRIN2B gene have been found in human patients with mental retardation." (PMID 25270331, 2014). "Phenotypes of GRIN2B-related disorders are highly variable among patients, ranging from mild intellectual disability without seizures to more severe encephalopathy." (PMID 40763259, 2025).